U6 (U6 spliceosomal RNA )
Synonyms: LOC124902333
Gene: Small nuclear RNA gene on chromosome 9 (64,082,429 to 64,082,534, forward strand). Ensembl gene ENSG00000275068.
Gene Ontology:
Molecular function: U4 snRNA binding
Biological process: formation of quadruple SL/U4/U5/U6 snRNP; spliceosomal tri-snRNP complex assembly
Cellular component: U4/U6 x U5 tri-snRNP complex; U6 snRNP
Homologues: Orthologues: chimpanzee U6 (99% identical), macaque U6 (92% identical), dog U6 (69% identical), mouse Gm54642 (59% identical), mouse Gm22279 (58% identical), rat LOC120101210 (58% identical). Paralogues in human: RNU6-1193P (97% identical), RNU6-1269P (97% identical), RNU6-368P (97% identical), RNU6-538P (97% identical), U6 (97% identical), RNU6-1320P (96% identical), RNU6-599P (96% identical), RNU6-316P (94% identical), RNU6-55P (94% identical), U6 (94% identical), RNU6-954P (93% identical), RNU6-821P (86% identical), and 1288 more.